NRAS (NRAS proto-oncogene, GTPase)
Diseases named in the same sentence as NRAS in open-access papers (continued):
Sharing a sentence is not in itself a finding about the gene and the disease.
melanoma (continued). "NRAS mutations are reported more frequently present in higher chronic sun-induced damage melanomas." (PMID 38183457, 2024). "Mutations in NRAS account for approximately 20% of all melanomas." (PMID 38247727, 2024). "To understand the mechanism of action of the T-RECS-targeting ASO treatment and how T-RECS may regulate the growth and survival of NRAS-mutated/MAPK-pathway driven melanoma tumor cells, we profiled the activity of kinase enzymes in melanoma samples." (PMID 38383439, 2024). "In addition, the presence of TERT promoter mutations is often associated with co-occurring mutations in BRAF or NRAS, indicating a synergistic effect on melanoma progression." (PMID 39200315, 2024). "We compared the expression level of AC004540.4 in biospecimens collected from healthy, non-cancerous skin samples banked in the GTEx database (n = 1,305 patient tissues), versus the collection of NRAS- or BRAF- mutated melanoma tumors available in the TCGA database (n = 366 patient tissues)." (PMID 38383439, 2024). "Indeed, an increase in the expression of gene encoding NRAS was observed in both resistant melanoma cell lines; this increase was 4-fold higher in WM9 R." (PMID 39175042, 2024). "Interestingly, we observed that the melanomas had a higher median NRAS G12/G13 mutational load than the nevi (1% versus 0.4%, p = 0.02)." (PMID 38396984, 2024). "Similarly, oncogenic mutations in the NRAS gene at codon 12, 13 and 61 are observed in various cancers including melanoma, colorectal cancer, and certain types of leukemia." (PMID 38982514, 2024). "NRAS mutations are identified in approximately 15–20% of tested melanomas." (PMID 38891988, 2024). "Advanced melanoma patients with NRAS and BRAF mutations respond better to treatment." (PMID 39195270, 2024). "High‐CSD melanoma frequently harbors NRAS, BRAF non‐V600E, and KIT mutations." (PMID 39564955, 2024). "NF1 co-mutations with either BRAF or NRAS, as well as frequently with other melanoma-associated oncogenes, suggest that this is overall a weaker oncogenic driver that may cooperate with additional MAPK pathway alterations to drive melanomagenesis." (PMID 38611025, 2024). "In addition, NRAS mutations frequently arise in BRAF-mutant melanomas as a mechanism of resistance in response to pharmacological inhibition of BRAF." (PMID 39379700, 2024). "Trametinib, a selective MEK inhibitor, is approved for the treatment of BRAFV600E-mutant melanoma and may also be effective in treating other melanoma subtypes, such as those with NRAS mutations." (PMID 38255375, 2024). "Three out of four patients who died from melanoma had either BRAF V600 or NRAS mutations." (PMID 38890171, 2024). "Furthermore, certain mutations within BRAF and NRAS melanoma-associated genes lead to overexpression of iNOS, subsequently promoting malignant cell survival through NO release and anti-apoptotic signaling." (PMID 39519202, 2024). "Additionally, melanomas treated with BRAF inhibitors tend to accumulate mutations in NRAS or MEK1/2, exhibiting excessive activation of ERK1/2 or SFK-STAT3." (PMID 38396984, 2024). "However, NRAS mutations dominate in melanomas, with mutations at position 61 appearing in ~20% of patients." (PMID 39576860, 2024). "In recent years, it has been identified that genetic factors, including activating mutations in the BRAF and NRAS oncogenes, contribute to melanoma initiation, promoting its growth and metastasis, as well as the transition of melanoma cells into different epithelial and mesenchymal states." (PMID 39099686, 2024). "However, NRAS is mutated in ~25% of melanomas, 20% of multiple myeloma, and more rarely in colorectal cancer (7.5%)." (PMID 39379700, 2024).
melanoma (continued). "Indeed, we found that treatment with T-RECS ASOs amplified the therapeutic efficacy of –and synergized with– the MEKi trametinib in NRAS-mutated melanoma tumor cells." (PMID 38383439, 2024). "BRAF V600 mutations were identified in 54% of melanomas, and NRAS G12/G13 mutations in 50%." (PMID 38396984, 2024). "Whether and how lncRNAs may be involved in melanoma progression or in NRAS-mutated/MAPK-dependent cancers, remains largely unknown." (PMID 38383439, 2024). "However, the therapeutic potency of existing drugs against melanomas with NRAS mutations is insufficient, highlighting the need to identify novel targets." (PMID 38462618, 2024). "Similarly, NRAS mutations, especially the Q61R variant, appear in 10–25% of melanomas, affecting cell proliferation and survival." (PMID 39519202, 2024). "The extracellular signal-regulated kinase (ERK) signal transduction pathway, which regulates cell proliferation, differentiation, and survival in response to extracellular stimuli, is constitutively activated in most malignant melanomas due to oncogenic mutations of NRAS or BRAF genes." (PMID 39436655, 2024). "The question of whether RIPK4 levels affect cisplatin sensitivity more in melanoma cells with BRAF mutations than in those with NRAS or BRAF wild-type mutations warrants further investigation in future studies." (PMID 39766280, 2024). "Besides, BRAF and CRAF collaborate to activate ERK and maintain proliferation in NRAS-mutated human melanoma cell lines." (PMID 38111008, 2023). "Another study that provides insights into the potential impact of MITF mutations on treatment response in the context of BRAF and NRAS mutations found that melanomas with concurrent NRAS and MITF mutations had distinct gene expression patterns and exhibited resistance to MAPK pathway inhibition." (PMID 37504268, 2023). "Mutations in NRAS gene have been correlated with poorer overall survival, and there is an unmet clinical urge for effective therapeutic approach for patients with this melanoma subtype." (PMID 37259298, 2023). "Here, we investigated and compared the molecular profile of BRAF and NRAS mutated and wildtype melanoma patients’ tissue samples using imaging mass spectrometry-based proteomic technology, to identify specific molecular signatures associated with the respective tumors." (PMID 36982192, 2023). "Overexpression of miRNA-708 successfully reduced NRAS protein levels in melanoma, leukemia, and lung cancer cell lines with NRAS mutations, resulting in suppressed cell proliferation, anchorage-independent growth, and promotion of reactive oxygen species-induced apoptosis." (PMID 37083947, 2023). "Finding effective therapeutic targets to treat NRAS-mutated melanoma remains a challenge." (PMID 38077055, 2023). "BRAF and NRAS mutations have been identified in 50% and 8% of melanoma, respectively." (PMID 36982192, 2023). "The authors suggested that the presence of MITF mutations might contribute to the resistance of NRAS-mutant melanomas to targeted therapies." (PMID 37504268, 2023). "Importantly, LXH254 produced promising preliminary antitumor efficacy in NRAS-mutated melanoma patients." (PMID 38111008, 2023). "Approximately 80% of melanomas contain either BRAF or NRAS activating mutations." (PMID 36588164, 2023). "The impact of NRAS mutations in anti‐PD‐1 adjuvant therapy of melanoma is highly debated." (PMID 37403699, 2023). "Activating mutations in NRAS account for 20%–30% of melanoma." (PMID 36583506, 2023). "Melanomas harboring NRAS mutations are a particularly aggressive and deadly subtype." (PMID 36765910, 2023). "Therefore, the aim of the present study was to test the applicability of this combination in vivo using three xenograft models as well as to bolster the concept that BRAF inhibitors enhanced the antitumor efficacy of MEK inhibitors in NRAS-mutated melanoma." (PMID 38067230, 2023).
melanoma (continued). "This study explores the therapeutic effect of the combination of BRAF and MEK inhibitors (BRAFi + MEKi) on NRAS-mutated melanomas in vitro, in preclinical in vivo models using patient-derived xenografts (PDXs) and in an individual healing attempt of one patient." (PMID 38067230, 2023). "A high proportion of NRAS mutations occur in melanoma patients." (PMID 37427373, 2023). "For the 45 patients with resected melanoma brain metastases undergoing targeted DNA sequencing, molecular classification recapitulated The Cancer Genome Atlas groups (NRAS variant, BRAF variant, NF1 variant, and triple wildtype) with no subtype enrichment within the brain metastasis cohort." (PMID 37589977, 2023). "Both components share an NRAS mutation, thus addressing the diagnosis of dedifferentiated melanoma." (PMID 37373134, 2023). "Mutations in NRAS are the second most common driver mutation in melanoma and lack therapy options." (PMID 36765834, 2023). "Besides, therapies for NRAS mutated melanoma are currently limited to immunotherapy or chemotherapy, as clinical trials targeting NRAS are just ongoing (see clinicaltrials.gov: NCT04835805)." (PMID 37179302, 2023). "It is well documented that oncogenic NRAS signaling facilitates cells to degrade the surrounding extracellular matrix by enhancing its proteolytic activity and thus increases the invasiveness of NRAS-mutated melanoma cells." (PMID 37083947, 2023). "Some of the most frequently occurring NRAS mutations in melanoma include Q61K, Q61R, and Q61L." (PMID 37504268, 2023). "Given that NRAS mutations are difficult to target, melanoma with NRAS mutation might be targeted using one or a combination of these drugs along with FDA-approved MEK inhibitors." (PMID 36765834, 2023). "The fact is that NRAS mutations occur predominantly in melanoma and the prognosis is dismal." (PMID 37465113, 2023). "BRAF V600 is the most encountered mutation in melanoma, followed by NRAS mutations." (PMID 37373134, 2023). "Serial hepatic passaging of NRAS mutated melanoma strongly affected its metastatic pattern." (PMID 37179302, 2023). "In addition to BRAF, other genes have been found mutated in sporadic melanomas including NRAS, TERT, NF1, and KIT." (PMID 37627054, 2023). "In this study we focused on NRAS mutated melanoma, a cohort with high unmet clinical need." (PMID 37179302, 2023). "Cg-Prkdcscid Il2rgtm1Wjl/SzJ) mice were subcutaneously injected with three different BRAF wild-type melanoma models harboring oncogenic NRAS mutations and treated orally with encorafenib (6 mg/kg body weight, daily) with or without binimetinib (8 mg/kg body weight, twice daily)." (PMID 38067230, 2023). "NRAS subtype: NRAS mutations (found in 15–20% of melanomas, but rare in nevi; they have a more aggressive clinical course) are caused by prolonged sun exposure, mostly found in nodular melanomas and melanomas with a Breslow index of over 1 mm." (PMID 36676131, 2023). "Our recent in vitro study unveiled a promising approach in which the BRAF inhibitor encorafenib, although being a V600E/K-specific inhibitor, had synergistic effects when combined with binimetinib in NRAS-mutated melanoma cells in terms of increased viability reduction and apoptosis induction." (PMID 38067230, 2023). "In addition, clinical studies have shown that melanoma with activating mutations in the NRAS gene is highly invasive and can rapidly develop resistance to existing treatment strategies." (PMID 37221594, 2023). "Therefore, we used the DDR gene sets from MSigDB to explore the differences in DDR pathway mutations between NOTCH4-Mut and NOTCH4-Wt tumors in NRAS-wildtype melanoma." (PMID 35967450, 2022).
melanoma (continued). "Interestingly, we demonstrated that in the absence of BRAF and CRAF, ARAF alone can sustain both ERK activation and proliferation in NRAS-mutated melanoma cells." (PMID 35091687, 2022). "The MassARRAY-based OncoFOCUS panel (v3) was previously adopted in our community pathology lab as a fully validated clinical test of common mutations in BRAF, EGFR, KIT, KRAS, and NRAS genes, which are implicated in various cancers, particularly colon cancer, lung cancer and melanoma." (PMID 35446881, 2022). "Although human BRAF- and NRAS-mutated melanomas have been associated with an increased risk for liver metastases, this association was rather weak and until now it has not been shown that one of these main driver mutations is a key determinant of hepatic metastasis." (PMID 35109875, 2022). "For examples, the BRAF inhibitor vemurafenib upregulates EMT gene expression in BRAF or NRAS mutated melanoma cells and promotes cell invasion and metastasis 50; the BRAF inhibitor PLX4032 enhances EMT in BRAF inhibitor-resistant thyroid cancer cell line 8505C cells." (PMID 36276640, 2022). "Interestingly, this interaction is conserved among the RAF protein kinase family since BRAF/MITF and CRAF/MITF complexes were also observed in the cytosol of NRAS-mutated mouse melanoma cells." (PMID 35091687, 2022). "Analysis of melanoma patients who developed BRAF inhibitor resistance revealed increased mitogen-activated protein kinase signaling from either development of NRAS and KRAS mutations in progressive tumors, or through 2- to 15-fold increase in BRAF mRNA compared with patient-matched baseline tumors." (PMID 35525274, 2022). "Therefore, many experiments have shown that in NRAS-mutated melanoma, the combination of multiple groups of inhibitors can effectively inhibit tumor growth." (PMID 35310910, 2022). "In other cases, mutations of c-kit or NRAS may serve as important pharmacological targets in advanced melanoma." (PMID 35380338, 2022). "LXH254 may thereby help overcome intrinsic and acquired resistance to BRAF-targeted therapy in BRAFV600-mutated melanomas and be a novel therapeutic approach for NRAS-mutated patients." (PMID 35380338, 2022). "Therefore, the MAPK pathway plays an important role in the occurrence and progression of NRAS mutated melanoma." (PMID 35310910, 2022). "Activating mutations in BRAF and NRAS are present in 50% and 25% of melanomas, respectively, and NF1, a protein that inhibits the RAS pathway, may also be inactivated in another 14% of melanomas." (PMID 36402789, 2022). "This study provides a new and feasible therapeutic strategy for melanoma carrying NRAS mutations." (PMID 36551302, 2022). "Recurrent BRAF and NRAS mutations are well documented in melanoma." (PMID 35326655, 2022). "However, the NRAS mutation has a role as an independent predictor, specifically in stage IV melanoma, as its expression predicts shorter survival." (PMID 36232957, 2022). "Mutations in NRAS have been found in 15–20% of mucosal melanomas, such as cutaneous ones." (PMID 35159047, 2022). "NRAS mutations are characteristic for less than 20%of melanoma cases." (PMID 35334544, 2022). "Based on in vitro studies, ERβ ligands inhibit NRAS mutation and thus the proliferation of melanoma cells, demonstrating that ERβ activation might weaken melanoma development by preventing the PI3K/Akt pathway." (PMID 36060947, 2022). "VM harbors NRAS mutation: exon 2 Q61 mutation is present in its Q61R/L/K/H variants, like 90% of melanomas with NRAS mutation (25% of all melanomas)." (PMID 36358637, 2022). "The percentage of NOTCH4 mutations is 9.4% (9/96) in NRAS wildtype melanoma." (PMID 35967450, 2022). "In vitro investigations suggested sensitivity of NRAS-mutated melanomas to MEK inhibition [38••]." (PMID 35380338, 2022).
melanoma (continued). "Cutaneous melanomas are classified into four subtypes: (i) mutation of the B-Raf proto-oncogene serine/threonine kinase (BRAFmut), (ii) mutation of the NRAS proto-oncogene GTPase (NRASmut), (iii) mutation of neurofibromin 1 (NF1mut), and (iv) none of the three, triple BRAF/NRAS/NF1 wild-type (WT)." (PMID 36428530, 2022). "Nevertheless, the association between NOTCH family gene mutations and clinical benefit in NRAS wildtype melanoma immunotherapy remains unknown." (PMID 35967450, 2022). "BRAF and NRAS gene mutations were also associated with shorter survival in melanomas." (PMID 35444210, 2022). "However, this correlation is weak as NRAS or BRAF mutations are found in approximately 80% of melanomas and cannot be used as reliable clinical predictor of hepatic metastasis." (PMID 35109875, 2022). "NRAS mutation is a relatively common mutation in melanoma cells." (PMID 35310910, 2022). "Besides the activating mutations in the BRAF and NRAS oncogenes, found in significant proportions of primary melanomas, important epigenetic changes occur in melanoma." (PMID 36443814, 2022). "All of BRAF V600E/K or NRAS Q61K/L/R driver mutations identified using the ArcherDX custom melanoma ctDNA panel and tissue biopsy were also identified using either ddPCR or a Thermofisher custom melanoma ctDNA panel." (PMID 35494035, 2022). "Although, oncogenic BRAF and NRAS mutations are usually mutually exclusive, they co-occur in approximately 7% of untreated melanoma and NRAS mutations confer resistance in 27% of BRAFV600-mutant melanoma patients who progress on combination BRAF and MEK inhibitor therapy." (PMID 35494035, 2022). "The potential role of ARAF in NRAS-induced melanoma was further strengthened by an in silico search in public databases that allowed to identify patients with metastatic melanomas harboring an ARAF mutation associated with activating NRAS mutations." (PMID 35091687, 2022). "Whether therapeutically targeting the ZBTB11 pathway would have a favourable outcome in NRAS mutated melanoma would require experimental evaluation." (PMID 35993275, 2022). "Mutually exclusive somatic TERT promoter mutations, C250T, C228T and CC242TT, were found in 48% (10/21) of the melanoma cohort and increased the overall ctDNA detection rate from 67%, based on detection of driver (NRAS or BRAF) or cancer-associated mutations, to 71%." (PMID 35494035, 2022). "Melanoma cells harboring NRAS mutations frequently exhibit resistance to MAPK kinase inhibitors." (PMID 35011702, 2022). "ARAF/MITF complexes were found in the cytosol of NRAS-mutated mouse melanoma cells." (PMID 35091687, 2022). "Therefore, for many years, the treatment of melanoma with NRAS mutation has mainly selected targeted inhibition of its related pathway enzyme components." (PMID 35310910, 2022). "Due to the limited samples, there are only a few melanoma cell lines with NRAS mutations." (PMID 35310910, 2022). "In addition, 10 out of the 19 patients have NRAS-mutated melanoma, a mutation that makes the tumor more pharmacologically susceptible to c-MET inhibition." (PMID 35954441, 2022). "Melanomas with NRAS mutations are often more aggressive and patients have a poorer prognosis." (PMID 34066022, 2021). "Similarly, increased overexpression of Sema6A, in NRAS mutated cells, induced anchorage-independent growth and enhanced invasion, thus, indicating Sema6A as a potential therapeutic target for melanoma treatment." (PMID 33858502, 2021). "To validate the 18 candidate regulators of the molecular networks underlying primary melanoma prognosis, we performed siRNA knockdown experiments in SKmel147 (NRAS mutant) and A375 (BRAF mutant) cell lines (see siRNA screening of candidate targets in Supplementary Methods)." (PMID 33619278, 2021).